CD80 (CD80 molecule)
Description:
Costimulatory molecule that belongs to the immunoglobulin superfamily that plays an important role in T-lymphocyte activation. Acts as the primary auxiliary signal augmenting the MHC/TCR signal in naive T-cells by acting as a ligand for the CD28 receptor which is constitutively expressed on the cell surface of T-cells. In turn, activates different signaling pathways such as NF-kappa-B or MAPK leading to the production of different cytokines. Also acts as an inhibitor of T-cell activation by acting as a ligand for CTLA4, a decoy receptor, thereby blocking CD28-mediated T-cell priming. In addition, CD28/CD80 costimulatory signal stimulates glucose metabolism and ATP synthesis of T-cells by activating the PI3K/Akt signaling pathway. Also acts as a regulator of PDL1/PDCD1 interactions to limit excess engagement of PDL1 and its inhibitory role in immune responses. Expressed on B-cells, plays a critical role in regulating interactions between B-cells and T-cells in both early and late germinal center responses, which are crucial for the generation of effective humoral immune responses (By similarity). (Microbial infection) Acts as a receptor for adenovirus subgroup B.
Synonyms: B7; CD28LG; CD28LG1; LAB7; B7.1; B7-1; BB1
Tractability: Antibody: a drug acting on it is in phase 2 or 3 trials; UniProt places it where antibodies can reach, with high confidence; its Gene Ontology location is reachable by antibodies, with high confidence; UniProt predicts a signal peptide or a membrane-spanning region. Other modalities: an approved drug acts on it.
Target class: Surface antigen
Gene: Protein-coding gene on chromosome 3 (119,523,898 to 119,569,324, reverse strand). Ensembl gene ENSG00000121594.
Subcellular location: Cell membrane
Pathways (Reactome):
Immune System: CD28 dependent PI3K/Akt signaling; CD28 dependent Vav1 pathway; Co-inhibition by CTLA4; Co-stimulation by CD28; Interleukin-10 signaling
Signal Transduction: PI5P, PP2A and IER3 Regulate PI3K/AKT Signaling; PIP3 activates AKT signaling
Disease: Constitutive Signaling by Aberrant PI3K in Cancer
Gene Ontology:
Molecular function: protein binding; receptor ligand activity; coreceptor activity
Biological process: negative regulation of T cell mediated immunity; positive regulation of peptidyl-tyrosine phosphorylation; positive regulation of T cell receptor signaling pathway; T cell activation; cell surface receptor signaling pathway; cellular response to lipopolysaccharide; immune response; intracellular signal transduction; negative regulation of T cell proliferation; positive regulation of DNA-templated transcription; positive regulation of granulocyte macrophage colony-stimulating factor production; positive regulation of interleukin-2 production; positive regulation of signal transduction; positive regulation of T cell proliferation; positive regulation of T-helper 1 cell differentiation; T cell costimulation; immune system process; positive regulation of immune system process
Cellular component: cell surface; plasma membrane; protein complex involved in cell adhesion; external side of plasma membrane
Genetic constraint (gnomAD): Loss-of-function variants: 9 observed, 19.2 expected, observed/expected ratio (o/e) 0.47, 90% interval 0.28 to 0.82. The upper end of that interval is the gene's LOEUF score, 0.82, which puts it in group 3 of 6, group 1 being the genes least tolerant of losing a copy. Missense variants: 230 observed, 299.44 expected, observed/expected ratio (o/e) 0.77, 90% interval 0.69 to 0.86. Synonymous variants: 104 observed, 110.57 expected, observed/expected ratio (o/e) 0.94, 90% interval 0.8 to 1.11.
Homologues: Orthologues: chimpanzee CD80 (99% identical), macaque CD80 (95% identical), rabbit CD80 (57% identical), pig CD80 (56% identical), dog CD80 (55% identical), rat Cd80 (45% identical), mouse Cd80 (42% identical). Paralogues in human: CD86 (23% identical), PDCD1LG2 (18% identical), CD274 (16% identical), RNF135 (9% identical), RFPL3 (6% identical), RFPL4B (6% identical), RFPL1 (5% identical), RFPL2 (5% identical), RFPL4A (5% identical), RFPL4AL1 (5% identical), SPRYD4 (4% identical), RNF152 (2% identical).
Diseases named in the same sentence as CD80 in open-access papers:
CD80 is named in the same sentence as 368 diseases in open-access papers, as found by Europe PMC text mining. Sharing a sentence is not in itself a finding about the gene and the disease. The quoted sentences say what the papers report.
melanoma (95 papers, 1998 to 2026). A malignant, usually aggressive tumor composed of atypical, neoplastic melanocytes. "We observed that CD80 blockade caused CD4 Teff accumulation in melanoma TILs and a concomitant decrease in dLNs, suggesting lymphatic migration was inhibited by blockade of CD80/PD-L1." (PMID 35449134, 2022). "An extensive search of human cancer databases indicates that the gain of CD40/CD80/ICOSL copy number in melanoma patients is associated with significantly better survival." (PMID 34092233, 2021). "The monocytes associated with melanoma are restrained in their expression of CD80 and CD86 co-stimulatory molecules but retain CD14 and HLA class II expression, thus finally promoting the expansion of CD11b+/Gr-1+ MDSCs." (PMID 29755693, 2018). "In this study, DCs derived either from in vitro differentiated monocytes or ex vivo from melanoma-draining SLN were transduced with CD80/CD86-targeted fiber-modified Ad5/3 encoding full-length MART-1." (PMID 30022005, 2018). "Selective blockade of CD28 signalling, either with anti-CD80/CD86 or cytotoxic lymphocyte-associated antigen-4 (CTLA4)-Ig (soluble protein binding to CD80/86), has been applied clinically in the treatment of autoimmune diseases, such as rheumatoid arthritis, and in melanoma." (PMID 36675078, 2023). "Interestingly, we determine PD-L1 therapy as lower in efficacy compared to PD-1 therapy for melanoma, which may be a consequence of the associated checkpoints (i.e., CD80, PD-1 and PD-L2, expressed at literature reported averages for melanoma)." (PMID 31375756, 2019). "In melanoma, we identified an 8-gene signature (CD28, CD80, CD86, CTLA4, FAS, IFNG, IL10, and IL12A) associated with survival." (PMID 42216340, 2026). "When CD80 expression was examined, it was significantly higher in the superficial spreading melanoma and lentigo maligna melanoma subtypes than in other subtypes." (PMID 37614091, 2024). "CD80 staining scores were higher in superficial spreading melanoma and lentigo maligna melanoma subtypes when evaluating CD80 staining scores." (PMID 37614091, 2024). "SLN LCs in patients with melanoma are functionally defective (low CD80/86 co-stimulatory molecules), immature (low CD83), and express IDO enzymes." (PMID 38791968, 2024). "Mortality was lower in superficial spreading melanoma and Lentigo maligna melanoma types, whereas staining positivity of CD80 and CD86 was higher." (PMID 37614091, 2024). "Studies have shown that the circadian clock gene BMAL1 affects dendritic cells (DCs) and CD8 T cells through the co-stimulatory molecule CD80, thereby exerting circadian anti-tumor functions that control melanoma volume." (PMID 37323834, 2023). "Photodynamic therapy (PDT) with redaporfin stimulates colon carcinoma (CT26), breast (4T1) and melanoma (B16F10) cells to display high levels of CD80 molecules on their surfaces." (PMID 37468749, 2023). "By exploring pDC diversity, we observed an increased frequency of P3-pDCs (CD80+PD-L1−) in the blood of melanoma patients compared to healthy volunteers, together with their accumulation within the tumor, which was linked to a bad clinical outcome." (PMID 37190135, 2023). "Using flow cytometry, we found that CD79b+ neutrophils expressed higher levels of the antigen presentation-related proteins, namely CD40, CD80, and HLA-DR, compared to other neutrophils in melanoma subjects." (PMID 38022639, 2023). "CD80 is expressed in various human tumors, such as melanoma, colon adenoma, and gastric adenocarcinoma, as well as in oncogenic cell lines, for instance, cell lines derived from melanoma, colorectal carcinoma, Burkitt’s lymphoma, and gastrointestinal cancer." (PMID 33923750, 2021). "Using qRT-PCR we observed an increased expression of IL-1β, CCL1, CCL2, and CD80 in transfected M1 macrophages, similarly to in M1 macrophages co-cultured with melanoma cells or treated with melanoma-derived exosomes." (PMID 32079286, 2020).
melanoma (continued). "In this sense, PDT-treated melanoma cells induced IFN-1-dependent phenotypic maturation of monocyte-derived dendritic cells (DCs) by enhancing co-stimulatory signals (CD80, MHC-II) and tumor-directed chemotaxis." (PMID 31781113, 2019). "The ability of CD80 to bind PD-L1 and prevent PD-1 binding was confirmed by assessing the binding of PD-1-Fc molecules to CD80+PD-L1+ and CD80−PD-L1+ human melanoma cells." (PMID 31001479, 2019). "Through co-expression of PD-1, CTLA-4, and PD-L1, melanoma cells are able to inhibit antigen presenting cells such as DCs by direct binding of CD80 and CD86 through CTLA-4 and by engagement of PD-L1 through PD-1." (PMID 31192129, 2019). "Consistent with a previous study on melanoma patients, we detected variable level of CD80, CD83 and/or CD86 expression on CD14+HLA-DR−/low MDSC in the PB and/or ascites from OC; however, their functional significance remains elusive." (PMID 29100353, 2017). "The melanoma microenvironment in particular leads to local T-cell tolerance in part through down-regulation of co-stimulatory molecules, such as B7.1 (CD80)." (PMID 28589082, 2017). "The administration of IL-18 also induced anti-tumor immunity in mice bearing B16 melanoma tumors expressing B7-1 (CD80)." (PMID 26378020, 2015). "It was also shown that administration of IL-18 induced anti-tumor immunity in mice bearing B16 melanoma tumors expressing B7-1 (CD80)." (PMID 24273542, 2013). "We have previously shown that melanoma cells expressing high levels of CD70 alone or in combination with CD80 induced in vitro splenocyte proliferation." (PMID 15279677, 2004). "Moreover, a low expression of CD80 resulting in T cell co-stimulation has been detected in several tumor entities, such as colon carcinoma and melanoma." (PMID 40649953, 2025). "Previously, we have reported that the in vitro stimulation with the melanoma cell lysate TRIMEL to primary human AM cells mediated up to four-fold induction of several surface markers associated with DCs maturation such as MHC-I, MHC-II, CD80, CD83, and CD86." (PMID 35805888, 2022). "Similarly, CD80, CTLA4 and CD66 genes that involve in CTLA4/CD80-86 signaling pathway for T cell inhibition were also significantly highly expressed in low risk melanoma patients." (PMID 34040608, 2021). "Given that RGS treatment in mice increased CD40, CD80, and ICOS-L expression levels on tumor cells, and this was associated with a better therapeutic outcome, we questioned whether the levels of CD40/CD80/ICOS-L have any prognostic value in melanoma patients." (PMID 34092233, 2021). "In our study, CD80 expression was increased as the melanoma growth phase advanced." (PMID 33669410, 2021). "On the other hand, CD80 expression was also increased in advanced growth-phase melanoma." (PMID 33669410, 2021). "Increased CD80 expression on melanoma-exosome-primed macrophages may lead to an inhibition of activated T-cell proliferation and function." (PMID 32079286, 2020). "Furthermore, we detected the expressions of CD86 and CD80 on the tumor-infiltrating NK cells in vivo 10 days after injection of B16 melanoma cells." (PMID 24349559, 2013). "To assess the downstream effect of transligation between aT-sEV PD-1/CD80 and tumour cell PD-L1, we then evaluated the expression level of tumour PD-L1 following aT-sEV treatment in a panel of tumour cell lines, including human oral cancer, melanoma, breast cancer and lung cancer cell lines." (PMID 38719909, 2024). "Indeed, the rhythmic trafficking of DCs to the melanoma tumor draining lymph node governs a circadian response of tumor antigen-specific CD8+ T-cells that is dependent on the circadian expression of the co-stimulatory molecule CD80." (PMID 37190135, 2023). "We have previously reported that the addition of the heat shock-conditioned melanoma lysate TRIMEL to IL-4/GM-CSF-activated monocytes (AM) mediates the induction of canonical surface markers associated with DC maturation such as MHC I, MHC II, CD80, CD83, and CD86." (PMID 31886313, 2019).
melanoma (continued). "Therefore, PD1 and CD28 expression by T-Exo may be a valuable tool in predicting the best responders to immunotherapy among patients with melanoma, while CD80 and CD86 levels may serve as prognostic biomarkers." (PMID 29755693, 2018). "We previously demonstrated that murine B16F10 melanoma cells present a modified phenotype following in vitro treatment by mIFN-γ in association with GGTI-298, characterized by an up regulation of MHC-I and the GGTI-induced expression of CD80 and CD86 costimulatory molecules." (PMID 20140259, 2010). "Finally, in the melanoma cohort, the presence of <49% Ecad+ cancer cells, and more than 22% Vim+ cancer cells, 16% CD80+ cancer cells, 18% CD155+ cancer cells, and 9% Ecad−Vim+, Ecad−CD80+ and Ecad−CD155+ cancer cells might be risk factors for tumor relapse after adjuvant anti-PD-1 therapy." (PMID 38914547, 2024). "Accordingly, elevated CD80 and CD86 levels were observed in macrophages co‐cultured with irradiated melanoma cells." (PMID 38286661, 2024). "The expression of E-cadherin/Vimentin/CD80/CD155 proteins in cSCC, HNSCC and melanoma patient samples predicts response to anti-PD-1/PD-L1 therapy." (PMID 38914547, 2024). "Material and Methods: Hematoxylin and eosin staining and immunohistochemical staining for CD80, CD86, and PD-L1 were evaluated for clinical data, survival, prognosis, tumor location, malignant melanoma subtypes, tumor size, and prognostic findings." (PMID 37614091, 2024). "As a result, CD80 and CD86 immunohistochemical markers predict the prognosis of malignant melanoma cases." (PMID 37614091, 2024). "Histologic subtype analysis revealed that CD80 and CD86 expression was significantly higher in superficial spreading melanoma and lentigo maligna melanoma." (PMID 37614091, 2024). "A contributing factor to the lack of optimal CD4+ T cell activation is the absence or low levels of the co-stimulatory molecules CD80 and CD86 on melanoma cells." (PMID 35162988, 2022). "Previous studies have shown that panobinostat treatment resulted in the up-regulation of CD80 and MHC class I in melanoma cells." (PMID 35203582, 2022). "Mature DCs express a plethora of co-stimulatory markers, including CD80 and CD86 (cluster of differentiation 80 and 86, respectively), which are essential for activation of melanoma-specific T cells." (PMID 35248056, 2022). "Thus, the increased frequencies of IFNγ-producing Tregs or CD4 Teffs, and granzyme Bhigh CD8 Teffs in TILs by anti-PD-1 and anti-CD80 treatment may all have contributed to the melanoma regression, suggesting a potential combination therapy for melanoma with PD-1 and CD80 Abs." (PMID 35449134, 2022). "Within this context, we observed a trend to increased TNF-α, IFN-α-2a and IFN-λ1 secretion as well as an increased expression of CD80, PD-L1 and HLA-ABC by the BDCA-1+/BDCA-3+ myDC after treatment with supernatant from T-VEC treated melanoma cells." (PMID 34777344, 2021). "We next conducted 6-color (hematoxylin, CD40, CD80, CD11c, CD8 and SOX10) multiplex IHC staining on the section of tumors from melanoma patients treated with BRAF inhibitor." (PMID 34092233, 2021). "Through protein expression scanning by the Human Protein Atlas, overexpression of FLI1, CD28, CD80, and IL21R was discovered in melanoma." (PMID 33971970, 2021). "At the mechanistic level, RGS monotherapy and in combination with ICB sensitizes tumors to immune activation via induced immunogenic cell death (ICD), associated with upregulation of costimulatory signals (such as CD40, CD80, and ICOS-L) on melanoma cells." (PMID 34092233, 2021). "Specifically, treatment with INAPs-PTT increased the expression of co-stimulatory markers CD80 and CD86 on melanoma cells in vitro." (PMID 31963449, 2020). "While PTT alone (ICG-PLGA-PTT) increased CD80, CD86, and MHC-I expression, the addition of NextA further increased these expression levels on melanoma cells in vitro." (PMID 31963449, 2020).